RFC4 (replication factor C subunit 4)
Diseases named in the same sentence as RFC4 in open-access papers (continued):
Sharing a sentence is not in itself a finding about the gene and the disease.
tumor (continued). "By integrating the findings of RFC4 expression with MDSC and NKT cell infiltration, it can be inferred that the increased expression of RFC4 may indicate an inadequate immune response toward tumor growth." (PMID 38399367, 2024). "These researches suggest that RFC4 may play a critical role in maintain homeostatic tumour survival and has the potential to be a promising target for cancer therapy due to its remarkable ability to regulate cell division and proliferation." (PMID 39031628, 2024). "Through a tumor-infiltrating immune analysis, we found that RFC4 and GMPS were correlated with some tumor-infiltrating immune cells and that an increased expression of RFC4 and GMPS could result in a poor prognosis." (PMID 34520390, 2021). "Studies had shown that the over-expression of RFC4 in tumor tissues was related to the poor prognosis of HCC, and it could be potential therapeutic targets for HCC36." (PMID 33750838, 2021). "A possible reason might be that RFC4 was highly expressed throughout the cell circle process of proliferating cells, and tumor proliferation in situ will become slow with the development of the disease, which means a decrease in the expression of RFC4." (PMID 33344075, 2020). "Therefore, speculating that RFC4 expression may regulate the infiltration level of tumor immune cells and the immune response, ultimately affecting the prognosis of patients with cancer, is reasonable." (PMID 40612960, 2025). "This study primarily focused on exploring the potential association between RFC4 expression and malignant tissue by investigating two distinct cell types: MDSC, characterized by its immunosuppressive functions in cancer, and NKT, known for its distinct anti-tumor properties." (PMID 38399367, 2024). "The expression of RFC4 could indicate the immunotherapy efficacy of some tumours." (PMID 39031628, 2024). "Therefore, any perturbation in the functioning of RFC4 may play a role in cellular proliferation and tumor formation, and its aberrant expression has been recognized as a potentially significant prognostic indicator for a range of cancer types." (PMID 38399367, 2024). "Moreover, to further investigate the association between the expression levels of RFC4 and GMPS and the clinicopathological features in ESCC, we divided the 46 tumor samples into two groups according to the cutoff values (median of RFC4, mean of GMPS) of RFC4 and GMPS mRNA expression levels." (PMID 34520390, 2021). "Further analysis involved comparing the expression of RFC4 in normal tissues and OSCC tumor tissues by examining data from the GEO database." (PMID 39673181, 2025). "Additionally, we sought to explore various aspects of the functionality of RFC4, including its activation status, involvement in immune cell infiltration, genetic modifications, methylation patterns, prognostic significance, and molecular interactions within the tumor microenvironment (TME)." (PMID 38399367, 2024). "The RFC family consists of five protein subunits, RFC1, RFC2, RFC3, RFC4, and RFC512; which are strongly connected with tumor growth and metastasis." (PMID 38504096, 2024). "Compared to the paired normal tissues, the results showed that RFC4 and GMPS were upregulated in the ESCC tumor tissues." (PMID 34520390, 2021). "We only found 5 DEGs (BIRP1, PARP1, RFC4, RMI2, and RAD51) had protein expression data in HPA and the results showed that the expression levels of BIRP1, PARP1, RFC4, RMI2, and RAD51 in BRCA tumor tissues were higher than in normal tissues." (PMID 34408776, 2021). "However, as RCF4 expression also significantly correlates with cell proliferation markers in human NSCLC tissue, the oncogenic effects of RFC4 on cell proliferation, tumorigenicity and tumor metastasis could together contribute to the worse outcomes of NSCLC patient prognosis." (PMID 33976158, 2021).
tumor (continued). "Previous studies have confirmed that MCM2, BIRC5, and RFC4 are abnormally highly expressed in HCC, and that they participate in the regulation of HCC tumor biology." (PMID 31534853, 2019). "Differential gene expression analysis revealed 3155 DEGs (differentially expressed genes), among which six AAA ATPase genes (TRIP13, CHTF18, RFC4, ATAD2, FIGNL2, ATAD5) were significantly overexpressed in tumor samples compared to levels in normal samples." (PMID 31533816, 2019). "A statistically significant negative correlation between RFC4 expression and methylation was found in most tumours, indicating that methylation‐mediated RFC4 gene expression plays a crucial role in tumour development." (PMID 39031628, 2024). "It is important to highlight that within the investigated panel, no tumor exhibited a negative connection between RFC4 expression and MDSC invasion." (PMID 38399367, 2024). "Human replication factor C subunit 4 (RFC4) is a member of the RFC family that is often overexpressed in cancer, promoting tumor progression and resulting in worse survival outcomes by regulating tumor cell proliferation and cell cycle." (PMID 34408776, 2021). "However, a low expression of RFC4 and GMPS with a high expression of some tumor-infiltrating immune cells showed a good prognosis." (PMID 34520390, 2021). "Compared with other genes, MCM2, TOP2A, CDC45, KNTC1, RFC4 and RMI2 were highly expressed in CESC tumor tissues and might be better indicators of prognosis." (PMID 34174849, 2021). "In summary, our study shows that RFC4 and GMPS have potential as biomarkers for the early diagnosis of ESCC and may played a crucial role in the process of tumor immunity in ESCC." (PMID 34520390, 2021). "Possible relationships amongst RFC4, immune cells, and related genes were investigated using Cell-type Identification by Estimating Relative Subsets of RNA Transcripts (CIBERSORT) and Estimation of STromal and Immune cells in MAlignant Tumor tissues using Expression (ESTIMATE)." (PMID 40458559, 2025). "However, the expression levels of RFC1, RFC2, RFC3, and RFC4 did not exhibit significant differences in various tumor stages." (PMID 38504096, 2024). "Therefore, we measured the expression levels of RFC4 and GMPS in 46 pairs of ESCC tumor samples and adjacent normal tissues to prove RFC4 and GMPS were increased in ESCC." (PMID 34520390, 2021).
cancer (30 papers, 2008 to 2025). A tumor composed of atypical neoplastic, often pleomorphic cells that invade other tissues. "In a similar direction, the analysis of the GEPIA2 database depicted a positive association between RFC4 expression and these cancer types: ACC, BRCA, KICH, KIRC, KIRP, LIHC, and OV." (PMID 38399367, 2024). "RFC4 has been implicated that it plays an important role in the initiation and progression of cancers, but a comprehensive analysis of the role of RFC4 in cancer has not been performed." (PMID 39031628, 2024). "The underlying mechanism appears to involve RFC4, which promotes cancer cell proliferation, while reducing the RFC4 levels induces the formation of an enriched population of CRC cells in the S phase and a decrease in CRC cells proliferation." (PMID 25407051, 2014). "Although RFC4 expression is associated with immune and clinical survival in human malignant tumours, it is unclear whether RFC4 affects clinical survival through immune pathways." (PMID 39031628, 2024). "Furthermore, RFC4 was closely associated with immune cell infiltration in various cancers." (PMID 39031628, 2024). "In the present study, we first explored the expression of RFC4 in multiple cancers using a pan-cancer analysis." (PMID 40458559, 2025). "The expression level of RFC4 was significantly upregulated in most cancer tissues compared to that in normal tissues in TCGA samples." (PMID 40458559, 2025). "Overall, the expression of RCF4 in CC was correlated with positive anti-cancer cells, which further explains why high RFC4 expression is an indicator of good prognosis." (PMID 40458559, 2025). "Replication factor C subunit 4 (RFC4), an oncogene active in various human cancers, has been rarely studied in OSCC." (PMID 39673181, 2025). "Replication factor C subunit 4 (RFC4) is crucial for initiating DNA replication via DNA polymerase δ and ε and is overexpressed in various cancers." (PMID 40612960, 2025). "Consistent with previous reports, RFC4 was highly expressed in various cancers, indicating its involvement in the tumorigenesis." (PMID 40458559, 2025). "Overall, the biological role of RFC4 is complex, mainly manifested in its potential to promote cancer development in the early stages." (PMID 40458559, 2025). "RFC4 is involved in cancer cell cycle and growth pathways and has a high immune infiltration and proliferation score." (PMID 39031628, 2024). "To address this objective, we employed a pan-cancer analysis to investigate the oncogenic characteristics of RFC4." (PMID 38399367, 2024). "Various bioinformatics tools were used to analyze RFC4 as a potential oncogene and therapeutic target across many cancers." (PMID 38399367, 2024). "This study fully elucidates RFC4’s carcinogenic activities, emphasizing its potential as a prognostic biomarker and a target for anti-cancer therapy." (PMID 38399367, 2024). "The genes assayed were neuroendocrine-associated genes (INSM1, ASCL1, NRCAM, and SNAP25), one gene centered in the gene regulatory network (NUF2), and five possibly cancer-associated genes (PTP4A3, RFC4, REST, APEH, and FBLN2)." (PMID 34395507, 2021). "Remarkably, the present work also demonstrated that higher expression of UBE2T, RFC4, POLQ, BRIP1, and H2AFX is especially associated with worse overall survival (HR > 5) in several types of cancer (Group A and D)." (PMID 34853396, 2021). "Human replication factor C4 (RFC4) is involved in DNA replication as a clamp loader and is aberrantly regulated across a range of cancers." (PMID 25407051, 2014). "Western blot analysis also revealed overexpression of RFC4 in 12 of 16 cancer tissues that had analyzed by qPCR, compared with normal colonic tissues." (PMID 25407051, 2014).
cancer (continued). "Although emerging evidence has demonstrated that RFC4 plays an oncogene role in many human cancers, its expression patterns and functions in LUAD remain unclear." (PMID 40612960, 2025). "Previous studies have shown that RFC4 is required for cancer cell proliferation and may play a pivotal role in tumorigenesis in most cancer." (PMID 40458559, 2025). "Until recently, the role of RFC4 in cancer progression remained underexplored or unclear." (PMID 40612960, 2025). "RFC4 may play a crucial role in cancer cell survival, and because of its significant ability to regulate cell division and proliferation, it may be a promising target for cancer therapy." (PMID 40612960, 2025). "Overall, RFC4 acts as a positive anti-cancer gene, suggesting that the development of immunotherapy based on RFC4 may have little effect, which can help in planning research." (PMID 40458559, 2025). "Furthermore, the study endeavored to evaluate the potential of targeting RFC4 for developing novel antitumor therapeutics, thereby contributing to the advancement of cancer treatment strategies." (PMID 38399367, 2024). "Abnormal expression of RFC4 was found in different types of cancer used TCGA and GTEx data." (PMID 39031628, 2024). "We investigated the role of RFC4 in cancer using molecular biology methods." (PMID 39031628, 2024). "In addition, due to the limited number of normal samples in the TCGA database, we combined the TCGA data with the GTEx database to assess RFC4 expression in 33 cancer types." (PMID 39031628, 2024). "Alternative splicing of RFC4 was detected in different cancers." (PMID 39031628, 2024). "Bioinformatics analysis provides important information on the role of RFC4 in malignant tumours." (PMID 39031628, 2024). "Correlation analysis between RFC4 and checkpoint gene expression in different types of cancers showed a high correlation with immune genes including CCL4, CCL16, HLA family genes, TNFRSF8, TNFRSF14, TNFRSF18, CD70, CD44 (p < 0.05), CD276, CX3CL1 and VGEGFA (p < 0.05)." (PMID 39031628, 2024). "We analysed RFC4 protein expression levels in various cancers in the CPTAC database." (PMID 39031628, 2024). "Many reports have shown that RFC4 may play an important role in the proliferation, progression, invasion, and metastasis of cancer cells." (PMID 34520390, 2021). "Finally, we screened for RFC4-inhibiting pharmacological compounds with anti-cancer potential." (PMID 38399367, 2024). "RFC4 expression was significantly upregulated in LUAD, which is consistent with its expression in other cancers." (PMID 40612960, 2025). "While previous studies have suggested that RFC4 affects the development of HCC, further research is needed to fully understand its role in these cancers." (PMID 39031628, 2024). "By conducting an online TCGA analysis, we found that the expression of RFC4 and GMPS was upregulated in many cancers." (PMID 34520390, 2021). "The relationship between RFC4 and TIME was studied by Cell-type identification by estimating relative subsets of RNA transcripts (CIBERSORT) and Estimation of Stromal and Immune cells in Malignant Tumor tissues using Expression data (ESTIMATE)." (PMID 40612960, 2025). "Furthermore, the MYC, DDX21, USP7, RFC4, APEX1, CDK9, and NOP2 of the “cancer cells_vs_all-PDAC” group play a critical role in the metabolic reprogramming of the PDAC, contributing to the poor prognosis of PDAC." (PMID 40906153, 2025). "The protein network of unique cancer cell genes in the “cancer cells_vs_all-PDAC” group exhibited top 10 hub genes, including H4C6 (HIST1H4A or HIST1H4C), MYC, H3C12 (HIST1H3A or HIST1H3D), DDX21, USP7, RFC4, APEX1, CDK9, H2BC9 (HIST1H2BH), and NOP2." (PMID 40906153, 2025).
RFC4 also shares sentences with these, for which no sentence is quoted: non-small cell lung carcinoma (4 papers); prostate carcinoma (4); cervical (2); head and neck squamous cell carcinoma (2); skin cutaneous melanoma (2); acute lymphoblastic leukemia (1); acute myeloid leukemia (1); adenocarcinoma (1); Bladder Urothelial Carcinoma (1); cervical squamous cell carcinoma (1); colorectal adenocarcinoma (1); diffuse large B-cell lymphoma (1); Fanconi anemia complementation group A (1); fibrosarcoma (1); glioblastoma (1); head and neck cancer (1); Kidney Chromophobe (1); leukemia (1); lung (1); Malignant Fibrous Histiocytoma (1); myxofibrosarcoma (1); ovarian carcinoma (1); pleomorphic liposarcoma (1); round cell liposarcoma (1); squamous carcinoma (1); squamous intraepithelial lesions (1); type 2 diabetes (1).